HMGN2P46 (high mobility group nucleosomal binding domain 2 pseudogene 46)
Synonyms: D-PCa-2; FLJ39426; formerly C15orf21
Gene: Transcribed processed pseudogene on chromosome 15 (45,555,482 to 45,555,971, forward strand). Ensembl gene ENSG00000179362.
Diseases named in the same sentence as HMGN2P46 in open-access papers:
HMGN2P46 is named in the same sentence as 2 diseases in open-access papers, as found by Europe PMC text mining. Sharing a sentence is not in itself a finding about the gene and the disease. The quoted sentences say what the papers report.
prostate carcinoma (2 papers, 2013 to 2015). A carcinoma that arises from epithelial cells of the prostate gland. "HMGN2P46 is a pseudogene that is strongly expressed in AR-expressing prostate cancers but not expressed in AR-negative cancers in our cohort, suggesting an androgen regulated promoter." (PMID 25749039, 2015).
HMGN2P46 also shares sentences with these, for which no sentence is quoted: cancer (2 papers).